LASP1 (LIM and SH3 protein 1)
Diseases named in the same sentence as LASP1 in open-access papers (continued):
Sharing a sentence is not in itself a finding about the gene and the disease.
breast carcinoma (continued). "In the present work we investigated for the first time the expression of LASP-1 in a series of 83 invasive breast carcinomas at protein level and compared the data to clinically established breast cancer parameters." (PMID 17956604, 2007). "In earlier publications, overexpression of LASP-1 mRNA in metastatic lymph nodes derived from breast cancer patients, as well as the co-amplification of the gene together with HER-2/neu (c-erbB2) were demonstrated." (PMID 17211471, 2007). "A previous study also showed that LASP-1 mRNA is overexpressed in only 8–12% of all human breast cancers." (PMID 17956604, 2007). "Increased nuclear localization and cytosolic expression of LASP-1 was found in breast cancer with higher tumor stage as well as in rapidly proliferating epidermal basal cells." (PMID 17956604, 2007). "In this study we demonstrate that LASP-1 is not only a cytosolic, but also a nuclear located protein, which is highly overexpressed in breast cancer tissue compared to benign fibroadenomas." (PMID 17956604, 2007). "The Lim and SH3 domain protein LASP-1 was initially identified from a cDNA library of breast cancer metastases." (PMID 17211471, 2007). "LASP1 overexpression is reportedly correlated with poor prognosis in breast cancers; however, the cause of LASP1 overexpression has remained unclear (it does not result from CNAs)." (PMID 39322849, 2024). "LASP1, LIM, and SH3 domain protein 1, a cytoskeleton-associated protein involved in cancer cell migration and invasion, were initially identified in lymph nodes of human patients with breast cancer metastasis." (PMID 37345118, 2023). "The LASP1-AKT interaction was mainly studied in the context of breast cancer." (PMID 36497077, 2022). "In their study on ovarian cancer and breast cancer cell lines, they observed that altered expression of LASP-1 protein, which is a focal adhesion molecule, resulted in changes in the amount of ZYX in focal adhesions, which affected cell proliferation and migratory abilities." (PMID 35740950, 2022). "LASP1 is highly upregulated in breast cancer cells than that of normal breast cells." (PMID 35081873, 2022). "Furthermore, PPP1R14B-AS1, miR-134-3p and LASP1 were abundant in products immunoprecipitated by anti-Ago2 antibody in breast cancer cells." (PMID 37303940, 2021). "Thus, the miR-134-3p/LASP1 axis was found to be the effector of PPP1R14B-AS1 in breast cancer cells." (PMID 37303940, 2021). "Since we identified a relationship between miR-134-3p; its upstream regulator, PPP1R14B-AS1; and its downstream target, LASP1, the following experiments were performed to uncover the regulatory associations between PPP1R14B-AS1, miR-134-3p, and LASP1 in breast cancer cells." (PMID 37303940, 2021). "LASP1, a LIM protein subfamily, not only regulates cell apoptosis and cell cycle conditions but is also implicated in the control of proliferation, migration, invasion, and epithelial–mesenchymal transition in breast cancer." (PMID 37303940, 2021). "As a molecule originally identified from breast axillary lymph node metastasis, the overexpression and nuclear localization of LASP1 are closely related to the malignant progression of breast cancer cells and the overall survival rate of patients with breast cancer." (PMID 34862361, 2021). "Our study results affirmed that LASP1 could be overexpressed by PPP1R14B-AS1 in breast cancer cells via miR-134-3p sequestration." (PMID 37303940, 2021). "Furthermore, PPP1R14B-AS1 positively regulated LASP1 in breast cancer cells by imitating miR-134-3p." (PMID 37303940, 2021). "Interestingly, mechanical experiments revealed that targeting LASP1 was essential for producing miR-134-3p-dependent cancer-inhibiting actions on breast cancer cells." (PMID 37303940, 2021). "Using bioinformatics analysis, LASP1 was predicted as a candidate molecule that regulates miR-134-3p and was selected for research due to its considerable regulatory actions toward breast cancer genesis and progression." (PMID 37303940, 2021).
breast carcinoma (continued). "To confirm previous observations of the effect of LASP1 knockdown on AKT1 phosphorylation, we performed experiments with MDAMB-231 and MCF-7 breast cancer cells, stably transfected with doxycycline-inducible LASP1-specific shRNA, transiently transfected with different LASP1-specific siRNAs." (PMID 32075106, 2020). "In addition to breast cancer, LASP1 has also been shown to be important in the migration of lung and prostate cancer cells." (PMID 32872485, 2020). "Furthermore, the stable silencing of LASP1 inhibited breast cancer cell invasion through Matrigel; altered the gene expression of cell junction and extracellular matrix proteins." (PMID 32825729, 2020). "Additionally, the LIM and SH3 domain protein (LASP1) was identified as a functional target of miR-203a-3p as previously reported in other malignancies such as esophageal squamous cell carcinoma, breast cancer etc.." (PMID 28982387, 2017). "Overexpression of LASP1 in breast cancer may regulate gene transcription by recruiting zyxin to focal adhesions and induce tumor cell growth and migration." (PMID 27070597, 2016). "On the transcriptional basis, we observed reduced mRNA expression of MMP1, -3 and -9 after LASP1 knockdown in MDA-MB-231 breast cancer cells that could be confirmed on protein level." (PMID 27588391, 2016). "Furthermore, a nuclear LASP1 positivity is observed in several cancer entities and is correlated with worse patient outcome, at least, in breast cancer, and a transcriptional role for the protein is discussed." (PMID 27588391, 2016). "Therefore, we generated MDA-MB-231-shLASP1 cells, a highly LASP1 expressing invasive breast cancer cell line stably transfected with doxycycline-inducible shRNA against LASP1." (PMID 27588391, 2016). "Furthermore, analysis of publically available microarray data of low and high LASP1-expressing breast cancer probes revealed a significant higher c-Fos expression in LASP1-high tumor samples (p<0.001)." (PMID 27588391, 2016). "Besides, the actin-binding protein LASP1 was uniquely expressed in tumours and is also up-regulated in breast cancer to possibly support migration of cancer cells." (PMID 25872475, 2015). "Additionally, a co-overexpression of LASP1 with the ERBB2 (Her2/neu) oncogene was reported for human breast cancer tissues, as both genes are in close vicinity on the 17q11-21 region." (PMID 25622104, 2015). "Indeed, LASP1 and pLASP1-S146 are exclusively detected in the cytosolic fraction of the melanoma cell lines and NHEMs, while in breast cancer cells a distinct nuclear LASP1 signal is seen." (PMID 26061439, 2015). "LASP1 overexpression in breast cancer was confirmed by immunohistochemistry (IHC), using an immunoreactivity score, a semi-quantitative rating for cell staining: The score was significantly higher in invasive breast carcinomas compared to mammary fibroadenomas." (PMID 25622104, 2015). "LASP-1 expression and nuclear localization correlated significantly with tumor size, nodal positivity and a poor long-term survival of the patients affected by breast cancer." (PMID 25760690, 2015). "Concerning LASP1, the best-studied cancer entity to date is breast carcinoma." (PMID 25622104, 2015). "Similarly, a correlation between nuclear LASP1 localisation and poor overall survival is observed in breast cancer." (PMID 24980827, 2014). "Of the out-of-frame validated chimeras, we identified recurrent expressed chimeric transcripts involving CDK12 (2.7%) and RAE1 (1%), and DNA rearrangements involving C17ORF57 (0.5%), NSF (0.5%), USH2A (0.5%), and LASP1 (1%) from unselected breast cancers in external datasets 12,15–17,41–43." (PMID 24395524, 2014).
breast carcinoma (continued). "LASP-1 was identified originally from a cDNA library of metastatic breast cancer metastases." (PMID 24386158, 2013). "Increased LASP1 expression could lead to a more aggressive breast carcinoma phenotype, and knocking down LASP1 may reduce the migratory capacity of breast cancer cells, possibly by influencing the localization of zyxin." (PMID 22713668, 2012). "LASP1 was initially identified in a cDNA library prepared from breast cancer metastases." (PMID 22713668, 2012). "However, nuclear LASP-1-localisation in breast carcinomas is increased during proliferation with peak in G2/M-phase and correlated significantly with Ki67-positivity and poor OS." (PMID 20461080, 2010). "It is noteworthy that the LASP1 gene maps to a region (17q12) that is altered in 20–30% of human breast cancers and tumours bearing amplifications of 17q11-21 are associated with an adverse prognosis because of increased resistance to chemotherapy and endocrine therapy." (PMID 20461080, 2010). "Real-time PCR analysis confirmed upregulation of LASP1 mRNA in PDEF-deficient invasive and highly metastatic breast cancer cells (MBA-MB-231, BT-549), while in the non-invasive MCF-7 breast cancer cell line, endogenously expressing PDEF, a reduced LASP-1 protein level was detected." (PMID 20461080, 2010). "Therefore, the observed overexpression of the LASP-1 protein in more than 55% of human breast cancers is likely due to reasons distinct from gene amplification." (PMID 20461080, 2010). "Although only 30.7% of the invasive ductal carcinoma samples with cytosolic LASP-1 expression are positive for Ki67 staining, 68.7% of the breast cancer tissues with nuclear LASP-1 occurrence show positive staining for the proliferation marker Ki67 (χ2 test; P=0.04)." (PMID 20461080, 2010). "However, in this work, we analysed the expression pattern of LASP-1 in primary invasive breast cancers using micro-dissected tissues." (PMID 20461080, 2010). "There are two facts regarding LASP-1 that seem to be linked: (a) the prominent nuclear localisation of LASP-1 in primary breast cancer and (b) cell cycle arrest at G2/M accompanied by reduced cell proliferation after knockdown of LASP-1 in breast carcinoma cell lines." (PMID 20461080, 2010). "To further validate the influence of nuclear LASP-1 occurence on cell proliferation, we quantified the number of positive stained cells for the proliferation marker Ki67 in 30 breast cancer tissue samples with known high LASP-1 IRS⩾8 and either nuclear or cytosolic LASP-1 localisation." (PMID 20461080, 2010). "In a recent paper variable expression of LASP-1 in breast cancer was detected." (PMID 18419822, 2008). "MCF-7 breast cancer cells treated with IGF-I exhibit upregulated expression of LASP-1 as well." (PMID 18419822, 2008). "LASP-1 (L) protein expression was analyzed in 83 breast cancer samples." (PMID 17956604, 2007). "However, our immunohistochemical analysis provide evidence that the LIM and SH3 domain protein is highly expressed (LASP-1-positive) in 55.4% of all tested breast cancer samples." (PMID 17956604, 2007). "Interestingly, recent work has shown, that knock-down of LASP-1 in metastatic breast cancer cell lines BT-20 and MCF-7 results in a strong inhibition of proliferation and migration and leads to a reduction of zyxin at focal contacts through absence of LASP-1." (PMID 17211471, 2007). "Increased expression of LASP-1 in vivo is present in breast carcinomas with higher tumor stage and therefore may be related with worse prognosis concerning patients' overall survival." (PMID 17956604, 2007). "Thus, it is likely that among several focal adhesion proteins which are overexpressed in breast cancer LASP-1 has more regulative function than others." (PMID 17956604, 2007).
breast carcinoma (continued). "Furthermore, miR-134-3p overexpression evidently lowered LASP1 expression in breast cancer cells." (PMID 37303940, 2021). "Finally, findings demonstrating different phosphorylation patterns of LASP1 in breast cancer and chronic myeloid leukemia may have implications for CXCR4 function and tyrosine kinase inhibitor treatment." (PMID 32075106, 2020). "The effect of LASP1 on focal adhesion dynamics through its interaction with zona occludens 2 (ZO-2) and zyxin, as well as its impact on motility through association with the chemokine receptor CXCR4 and vimentin, suggests an intricate role for LASP1 in breast cancer metastasis." (PMID 32872485, 2020). "Moreover, miR-182 may also influence the nodal positivity and tumor size of breast carcinomas by regulating LASP1 expression." (PMID 30135399, 2018). "While analysis of microarray data for primary breast cancers revealed significant lower c-Fos mRNA levels in tumor samples with low LASP1 expression (p<0.001), the analysis of our microarray data set pointed to up-regulation of c-Fos transcription by LASP1 depletion." (PMID 27588391, 2016). "Moreover, the observed high cytoplasmic expression of LASP1 in breast cancer tissue correlated with a hitherto unknown nuclear LASP1-positivity." (PMID 25622104, 2015). "Breast cancer cells show high levels of LASP1 phosphorylated at S146 by PKA, while in chronic myeloid leukemia (CML) cells a dominant phosphorylation of LASP1 at Y171 by the constitutively active BCR-ABL tyrosine kinase was observed." (PMID 36497077, 2022). "LIM and SH3 protein 1 (LASP1) is a member of the LIM family of proteins, initially identified from a cDNA library of human breast cancer tissue." (PMID 36532732, 2022). "LASP1 interacts with the LKIL motif (aa 327–330) at the intracellular C-terminus of the chemokine receptors CXCR2 and CXCR4 which are overexpressed in breast cancer." (PMID 36497077, 2022). "LIM and SH3 protein 1 (LASP1) was identified as a tumor-promotion-related gene and its abnormal expression has been reported in several tumor types, including breast cancer, ovarian cancer, hepatocellular carcinoma, and CRC." (PMID 34615856, 2021). "In brief, PPP1R14B-AS1 can imitate miR-134-3p and antagonize the inhibitory effect of miR-134-3p on LASP1 in breast cancer cells, consequently constructing a novel PPP1R14B-AS1/miR-134-3p/LASP1 ceRNA pathway." (PMID 37303940, 2021). "In view of the new results and in combination with earlier published data, we propose a model that explains the divergent roles of LASP1 and CXCR4 in solid breast cancer and in CML cells." (PMID 32075106, 2020). "When LASP1 was stably knocked down in MDA-MB-231 (MDA-MB-231: ATCC® HTB-26TM, Manassas, VA, USA) breast cancer cells, there was an ablation of CXCL12-dependent invasion through Matrigel® (Matrigel: Discovery Labware, Inc., Bedford, MA, USA)." (PMID 32872485, 2020). "In conclusion, we postulate a model for the divergent CXCR4-LASP1-AKT1 signaling in breast cancer and CML by differences in LASP1 phosphorylation." (PMID 32075106, 2020). "Recent studies provided evidence that stable silencing of LASP1 also reduced gene expression levels of MMP9 and 1 in MDA-Bone-Un breast cancer cells (MDA-MB-231 cells that were re-isolated from mouse bone metastatic lesions)." (PMID 30298118, 2018). "By analyzing microarray data of in-house generated control and LASP1-depleted MDA-MB-231 breast cancer cells, we observed downregulation of MMP1, -3 and -9 upon LASP1 depletion." (PMID 27588391, 2016). "In breast cancer cell lines BT-20 and MCF-7 siRNA-mediated LASP1 knockdown led to decreased cell migration and proliferation." (PMID 25622104, 2015).
breast carcinoma (continued). "For cell localization of LASP-1 protein, data in the literature point the attention to the nuclear localization of LASP-1 in some cancers (e.g. breast cancer and HCC)." (PMID 25760690, 2015). "LASP1 protein contains one LIM, one SH3, and two actin domains, and was first discovered in 1996 as a protein that is over-expressed in breast cancer." (PMID 24580839, 2014). "In breast cancer, CRKL and LASP1 were shown to be overexpressed and to correlate with tumor growth and progression." (PMID 24913448, 2014). "For example, while the PDEF levels are similar in all three tested breast cancer cell lines (MDA-MB-231, BT-20, MCF-7) LASP-1 expression is only reduced in MCF-7 cells." (PMID 20461080, 2010). "LASP-1 regulates cell migration in 293-CXCR2 cells (in this study), mammary tumor and ovarian tumor cell lines and MEFS." (PMID 20419088, 2010). "Images taken with confocal microscopy confirmed nuclear localization of LASP-1 within the nucleus in BT-20 and MCF-7 breast cancer cells." (PMID 17956604, 2007). "Interestingly, strong nuclear LASP-1-positivity could be observed in about 29% of all breast carcinomas as well as in nuclei of epidermal basal cells, whereas all other breast carcinoma nuclei were negative for LASP-1 and the cells only displayed perinuclear and cytosolic LASP-1 enrichment." (PMID 17956604, 2007). "LIM and SH3 protein 1 (LASP-1), initially identified from human breast cancer, is a specific focal adhesion protein involved in cell proliferation and migration." (PMID 17211471, 2007). "In contrast to breast cancer cells and other solid tumors, LASP1 is not detected in the nucleus of CML cells, either in its tyrosine-phosphorylated form or after serine phosphorylation by forskolin-stimulated PKA activation." (PMID 32075106, 2020). "Based on the previous data showing a LASP1-mediated PI3K/AKT1 activation and our own findings demonstrating overexpression of LASP1 in breast cancer cells and in CML, we wanted to address whether there is a direct regulation of AKT1 by LASP1 in these cells." (PMID 32075106, 2020). "In addition, we investigate the differences in LASP1-CXCR4 signaling in breast cancer and CML, as these two tumor entities display different roles for CXCR4, despite comparable overexpression of the receptor binding-partner LASP1." (PMID 32075106, 2020). "Similarly, when LASP1 was stably silenced, E-cadherin level was rescued back in MCF7 and MDA-MB-361 luminal breast cancer cell lines in our previous studies." (PMID 32825729, 2020). "Overall, LASP1 effects on MMP expression are not restricted to breast cancer cells but are also not regulated alike in all cells." (PMID 27588391, 2016). "LIM and SH3 protein 1 (LASP1) was initially identified from metastatic axillary lymph nodes of breast cancer patients." (PMID 27156963, 2016). "Phosphorylation of LASP1 at Ser-146 by PKA is not inducing any translocation of the protein to the nucleus of the melanocytic cells as it is observed for the breast cancer cell line MDAMB231, which served as control." (PMID 26061439, 2015). "PDEF inhibits cell migration in multiple invasive breast cancer cells, and transfection of PDEF in three invasive breast cancer cell lines resulted in regulation of proteins involved in cytoskeleton regulation, including LASP1." (PMID 25622104, 2015). "Similarly to breast cancer and HCC, a nuclear LASP1 localization and overexpression has been confirmed for ESCC, mainly by confocal microscopy, immunohistochemistry, and Western blots of cytoplasmic and nuclear preparations." (PMID 25622104, 2015). "CDK12, LASP1, RAE1, C17orf57, NSF, and USH2A were partners of out-of-frame, but not in-frame, fusion genes here and in other massively parallel sequencing analyses of breast cancers 12,15–17,41–43." (PMID 24395524, 2014).